VNN1 (vanin 1)
Description:
Amidohydrolase that hydrolyzes specifically one of the carboamide linkages in D-pantetheine thus recycling pantothenic acid (vitamin B5) and releasing cysteamine.
Synonyms: Tiff66; HDLCQ8
Tractability: Small molecule: a structure with a bound ligand is known; a high-quality ligand is known. Antibody: UniProt places it where antibodies can reach, with high confidence; its Gene Ontology location is reachable by antibodies, with high confidence; UniProt predicts a signal peptide or a membrane-spanning region. PROTAC: its protein half-life has been measured; a small molecule that binds it is known.
Target class: Enzyme; Hydrolase
Chemical probes: PFI-653 (high quality)
Gene: Protein-coding gene on chromosome 6 (132,680,849 to 132,719,962, reverse strand). Ensembl gene ENSG00000112299.
Subcellular location: Cell membrane
Subcellular location (Human Protein Atlas): Vesicles
Pathways (Reactome):
Immune System: Neutrophil degranulation
Metabolism: Vitamin B5 (pantothenate) metabolism
Metabolism of proteins: Post-translational modification: synthesis of GPI-anchored proteins
Gene Ontology:
Molecular function: pantetheine hydrolase activity; hydrolase activity, acting on carbon-nitrogen (but not peptide) bonds, in linear amides
Biological process: pantothenate metabolic process; acute inflammatory response; cell-cell adhesion; chronic inflammatory response; inflammatory response; innate immune response; positive regulation of oxidative stress-induced intrinsic apoptotic signaling pathway; positive regulation of T cell differentiation in thymus; response to oxidative stress; coenzyme A catabolic process
Cellular component: azurophil granule membrane; extracellular region; membrane; plasma membrane
Genetic constraint (gnomAD): Loss-of-function variants: 29 observed, 44.26 expected, observed/expected ratio (o/e) 0.66, 90% interval 0.49 to 0.89. The upper end of that interval is the gene's LOEUF score, 0.89, which puts it in group 3 of 6, group 1 being the genes least tolerant of losing a copy. Missense variants: 637 observed, 653.32 expected, observed/expected ratio (o/e) 0.98, 90% interval 0.91 to 1.04. Synonymous variants: 233 observed, 235.51 expected, observed/expected ratio (o/e) 0.99, 90% interval 0.89 to 1.1.
Homologues: Orthologues: chimpanzee VNN1 (99% identical), macaque VNN1 (93% identical), dog VNN1 (80% identical), pig VNN1 (79% identical), rat Vnn1 (76% identical), guinea pig VNN1 (74% identical), mouse Vnn1 (74% identical), tropical clawed frog vnn2 (59% identical), Drosophila melanogaster Btnd (25% identical), Drosophila melanogaster vanin-like (25% identical), Drosophila melanogaster CG32750 (24% identical), Drosophila melanogaster CG32751 (23% identical). Paralogues in human: VNN2 (63% identical), BTD (40% identical).
Diseases named in the same sentence as VNN1 in open-access papers:
VNN1 is named in the same sentence as 90 diseases in open-access papers, as found by Europe PMC text mining. Sharing a sentence is not in itself a finding about the gene and the disease. The quoted sentences say what the papers report.
Obesity (9 papers, 2012 to 2026). Accumulation of substantial excess body fat. "Elevated levels of vanin-1 have been associated with increased risks of diabetes, obesity, and coronary artery disease." (PMID 40954177, 2025). "Elevated levels of VNN1 have been linked to chronic inflammation and metabolic disorders, such as obesity, T2DM, and non-alcoholic fatty liver disease (NAFLD)." (PMID 40458179, 2025). "On the contrary, Vanin‐1 deficiency impairs lipolysis in excess nutrient‐induced energy overload state, aggravating the development of adipocyte hypertrophy and obesity." (PMID 32714762, 2020). "Under pathological condition (HFD‐induced obesity), Vanin‐1 deficiency evokes increased adipose inflammation in addition to lipolysis inhibition, so that the combination of chronic inflammation and adipocyte hypertrophy aggravates glucose and insulin intolerance in these mice." (PMID 32714762, 2020). "In the current study we set out to study the effect of vanin-1 deficiency on the development of obesity-induced hepatic steatosis and diabetes, as well as the potency of RR6, a novel pantetheinase (vanin) inhibitor, as an anti-diabetic drug using experimental animal models." (PMID 26932716, 2016). "This suggests that the observed increase in vanin-1 expression in steatotic livers of obese mice, may rather be a marker of enhanced PPARα activation, without causal involvement of vanin-1 in the progression or prevention of steatosis during obesity." (PMID 26932716, 2016). "In this study, we aim to evaluate the biomarker potential of vanin-1 and PA together in the context of obesity, type-2 diabetes, and diabetes-related cardiovascular complications." (PMID 40954177, 2025). "This study investigated the relationship between vanin-1 and PA with obesity, type-2 diabetes (T2D), and related cardiovascular complications (CVD)." (PMID 40954177, 2025). "In future studies, we plan to further explore the correlation and mechanism between the Vanin family and obesity by studying the relationship between Vanin-1 and Vanin-2 factors and obesity, and potentially constructing human gene knockout mice." (PMID 38156278, 2023). "Previous research has demonstrated the crucial role of Vanin-1 in regulating lipolysis and obesity through PPAR-α and PPAR-γ." (PMID 38156278, 2023). "When Vanin‐1 is deleted in vivo, the basal lipolysis process will be severely impaired, leading to the net outcomes toward adipocyte hypertrophy and obesity." (PMID 32714762, 2020). "Vanin‐1 deficiency impaired lipolytic activity and increased macrophage infiltration in abdominal WAT of HFD‐fed mice, thus promoted the severity of obesity." (PMID 32714762, 2020). "Subsequently, we evaluated the role of vanin-1 in obesity-induced disturbances in glucose metabolism." (PMID 26932716, 2016). "In the present study, we investigated the role of vanin-1 in the development of hepatic steatosis and insulin resistance in animal models of obesity and diabetes." (PMID 26932716, 2016). "Additional studies are required to confirm and further understand the role of VNN1 in human obesity." (PMID 23185446, 2012). "Because VNN1 gene variants have not been previously found to be associated with obesity in GWAS and because the sample number analyzed here is reduced, these associations should be interpreted with caution." (PMID 23185446, 2012). "Thus, we concluded that the whole‐body Vanin‐1−/− mice exhibit adipocyte hypertrophy and obesity." (PMID 32714762, 2020). "BMI-predictive proteins included established obesity markers and obesity-related proteins, including adiponectin, CRP, IGFBP1, IGFBP2, PRG4, SHBG, apolipoproteins (APOA4, APOF) and inflammatory response proteins (A2M, APCS, LBP, HSPG2, HP, AOC3, ITGB1, VNN1)." (PMID 39972214, 2025).
diabetes (7 papers, 2016 to 2025). "As evident from our present study, this unclear understanding may arise from the differential role of vanin-1 and PA in diabetes and its associated CVD." (PMID 40954177, 2025). "Additionally, vanin-1-deficient animals displayed increased susceptibility to diabetes, suggesting impaired vanin-1 function may compromise tissue stress tolerance through reduced PA regeneration." (PMID 40954177, 2025). "To assess the relationship between vanin-1, PA, and the odds of diabetes and related cardiovascular diseases, we conducted a multinomial logistic regression analysis." (PMID 40954177, 2025). "To further investigate the role of vanin-1 in diabetes, we conducted a correlation analysis with the studied parameters." (PMID 40954177, 2025). "When comparing plasma vanin-1 levels among different study groups within the third tertile (> 1.574 ng/mL), patients with diabetes exhibited a trend toward elevated vanin-1 levels." (PMID 40954177, 2025). "Given that vanin-1 catabolizes pantetheine to both PA and cysteamine, this apparent discrepancy suggests a more complex regulation of the pathway in diabetes." (PMID 40954177, 2025). "To evaluate the impact of various diabetes medications on vanin-1 and PA levels, we performed a binary logistic regression analysis." (PMID 40954177, 2025). "An intriguing finding of our study is the tendency for increased vanin-1 concentration alongside lower PA levels in diabetes." (PMID 40954177, 2025). "Future studies should aim to elucidate the clinical implications of PA supplementation and vanin-1 inhibition as potential therapeutic strategies in managing diabetes and its complications." (PMID 40954177, 2025). "Our results further supported the involvement of VNN1 in the pathological process of diabetes, thus making VNN1 as an important biomarker candidate for the diagnosis of this disease." (PMID 34178943, 2021). "The variability in findings across studies may stem from differences in assessing vanin-1 activity, suggesting that its effects on diabetes may be tissue-specific." (PMID 40954177, 2025). "VNN1 expression was significantly increased in bone and serum from osteoporotic and diabetic mice, as well as in serum from patients with osteoporosis and diabetes." (PMID 38966541, 2024). "Notably, the prevalence of diabetes in the highest tertile of vanin-1 (n = 32) was 62.5% (n = 20)." (PMID 40954177, 2025). "Numerous functional studies demonstrate a role for Vanin genes [Vanin-1 (VNN1), Vanin-2 (VNN2), Vanin-3 (VNN3)] in inflammation, oxidative stress, cell migration, and various diseases such as diabetes and CVDs." (PMID 33597859, 2021). "While vanin-1 levels did not vary significantly across the groups, there was a noticeable trend toward higher levels in the diabetes cohorts." (PMID 40954177, 2025).
Hypertension (7 papers, 2007 to 2024). The presence of chronic increased pressure in the systemic arterial system. "In investigations on humans, urine vanin 1 served as both an independent risk factor for renal function decrease in hypertension and an initial indicator of kidney damage linked with CKD." (PMID 36648873, 2022). "Researchers genotyped a panel of 2270 variants in a random sample of 1743 African Americans and found a missense variant in Vanin 1 (VNN1) (rs2272996) that was significantly associated with hypertension in African Americans." (PMID 30832344, 2019). "Further analyses demonstrated that the missense SNP rs2272996 (or N131S) in the VNN1 gene was significantly associated with hypertension in African Americans and the association was replicated in Mexican Americans; a non-significant opposite association was observed in European Americans." (PMID 18043751, 2007). "We adapted this strategy in the chromosome 6 region and identified a missense SNP rs2272996 (or N131S) in the VNN1 gene significantly associated with hypertension in African Americans after adjusting for multiple comparisons; this association was replicated in Mexican Americans." (PMID 18043751, 2007). "A previous observational study in patients with hypertension reported that urinary vanin-1 correlated positively with urinary albumin and inversely with eGFR18." (PMID 38280883, 2024). "It was also discovered that urinary vanin 1 was detectable in experimental rats at the preliminary phase of hypertensive AKI." (PMID 36648873, 2022). "A further experiment demonstrated that atenolol and diltiazem, two current drugs for treating hypertension, reduce the vanin-1 protein level." (PMID 25233454, 2014). "Association with hypertension was identified at α = 0.05 significance level at rs2244008 (A/G) and rs2272996(C/T) in the LAMA2 and VNN1 genes, respectively." (PMID 18043751, 2007). "The present study provides a hypothesis that urinary vanin-1 might be a potentially sensitive biomarker of the ameliorating effect of drugs for oxidative tubular damage, especially in the salt-sensitive model of hypertension." (PMID 31514290, 2019). "Vanin-1 was expressed in the renal tubules and not in the glomeruli when there was oxidative injury in the salt-sensitive model of hypertension, with the marker of oxidative stress also co-localized in the renal tubules." (PMID 31514290, 2019).
inflammatory bowel disease (7 papers, 2016 to 2025). A spectrum of small and large bowel inflammatory diseases of unknown etiology. "Functional polymorphisms in the regulatory regions of the VNN1 gene are associated with susceptibility to inflammatory bowel disease." (PMID 36838374, 2023). "The polymorphisms of VNN1 gene is associated with susceptibility to inflammatory bowel diseases and participates in the regulation of gut inflammation." (PMID 28659929, 2017). "A stopgain mutation was found in BTNL9, a member of the butyrophilin family that plays a role in inflammatory bowel disease (IBD), and a novel frameshift mutation was found in VNN1, which affects the gut mucosal barrier." (PMID 40894167, 2025). "In the colon tissue of patients with inflammatory bowel disease (IBD), VNN1, an enzyme of the exogenous CoA-SH degradation pathway, is overexpressed." (PMID 33260564, 2020).
Sepsis (7 papers, 2021 to 2025). Sepsis is defined as life-threatening organ dysfunction caused by a dysregulated host response to infection. "For instance, plasma VNN1 is increased in trauma patients and is independently associated with the risk of sepsis." (PMID 36527111, 2022). "In our model, four genes (NR3C2, CEACAM1, VNN1, and SLC2A3) were linked to the development of AKI in patients with sepsis." (PMID 40765579, 2025). "VNN1 holds promise as a potential biomarker for sepsis diagnosis and is significant in identifying immune infiltration in tumor tissue and predicting tumor prognosis." (PMID 37608823, 2023). "Recently, some articles showed that inhibition of the VNN1 protein can alleviate the lung injury in sepsis and sepsis shock mice." (PMID 37608823, 2023). "In conclusion, the objective of our study is to search for potential biomarkers in sepsis based on fatty acid metabolism-related signatures, and finally VNN1 was screened." (PMID 37608823, 2023). "The expression of VNN1 in the healthy group was significantly lower than in the sepsis group." (PMID 37608823, 2023). "This study searched for a potential biomarker of sepsis (VNN1), which will help to further explore the mechanism of action of fatty acid metabolism in sepsis, the immune response in sepsis, and the relationship between sepsis and tumors." (PMID 37608823, 2023). "In contrast, OLAH and VNN1 showed low expression across all major immune cell types, suggesting that these genes may be expressed in non-immune blood components (e.g., endothelial cells or platelets) and contribute to sepsis progression through indirect mechanisms." (PMID 41333476, 2025). "The AUC value in the GSE134347 dataset can illustrate the importance of VNN1 in diagnosing sepsis and it can be validated in GSE69063 dataset by comparing the different expressions of VNN1 between the healthy group and sepsis group." (PMID 37608823, 2023). "Among the mRNAs related ygiM we verified, VNN1, CEACAM8, and PGLYRP1 were highlighted about sepsis firstly." (PMID 36212144, 2022). "AKT1, top up- (FKBP5, SORT1, VNN1, and CST7) and downregulated (PRR5L, SH2B3, SULF2, PLEKHO1, and PTPN6) genes in sepsis were validated using RT-PCR." (PMID 33959663, 2021). "Logistic regression was used to assess the likelihood of sepsis based on CA4, OLAH, and VNN1." (PMID 37608823, 2023). "After comparing the results of miRNAs and mRNAs, we identified hsa-miR-342-3p/VNN1, hsa-miR-7108-5p/CEACAM8, hsa-miR-4433b-3p/CEACAM8, and hsa-miR-342-3p/CEACAM8 as interactive pairs related ygiM that were statistically significant in sepsis." (PMID 36212144, 2022).
asthma (6 papers, 2019 to 2026). "Vanin-1, a well-recognized sensor of oxidative stress, has been implicated in various inflammatory disorders; however, its diagnostic value in asthma remains to be fully elucidated." (PMID 42082969, 2026). "The mRNA and protein levels of Vnn1 were dramatically increased (P<0.001) in cultured cells from the IUGR asthma mice, which was significantly (P<0.05) prevented by shRNA-Vnn1." (PMID 32139393, 2020). "The methylation frequency of Vnn1 promoter region was elevated in the IUGR mice following asthma induction." (PMID 32139393, 2020). "In a recent study, vanin 1 was found to be a biomarker of corticosteroid treatment response in children with asthma." (PMID 31404995, 2019). "Interestingly, the VNN1 gene has been found to be involved in asthma corticosteroid treatment and to be regulated at the protein level by pro-inflammatory cytokines." (PMID 34229738, 2021). "Therefore, this study aimed to investigate the regulatory role of Vnn1 on the PI3K/Akt signaling activity in the IUGR mice challenged with ovalbumin (OVA) in order to discover the potential molecular mechanisms of asthma in IUGR children." (PMID 32139393, 2020). "We found key asthma-associated genes including the T2-high signature genes of CLCA1, POSTN, and SERPINB2 as well as those not previously asthma-associated (e.g., CST1 and Vanin genes—VNN1–3) to be potentially influenced by aberrant H3K27ac." (PMID 33362848, 2020). "Asthma developed in Vnn1-knockout mice following a challenge by house dust mites." (PMID 32139393, 2020). "In contrast, vnn1 KO mice were unresponsive to dexamethasone treatment, demonstrating that vanin 1 contributes to an optimal response to corticosteroid treatment in experimental asthma." (PMID 31404995, 2019). "The expression level of Vnn1 in lungs was not altered in experimental mouse asthma models challenged by repeated allergen or IL-13." (PMID 32139393, 2020). "Absence of the Vnn1 gene resulted in resistance to dexamethasone treatment, which was reflected by persistent airway hyperresponsiveness and inflammatory cells in the lungs in an asthma mouse model." (PMID 32139393, 2020). "Interestingly, it was reported that the asthma patients with downregulation of the Vnn1 gene expression level were not sensitive to glucocorticoid therapy." (PMID 32139393, 2020). "Importantly, vanin 1 was not essential to asthma development, because vnn1 KO mice did develop an asthma phenotype, including airway inflammation." (PMID 31404995, 2019).
colitis (6 papers, 2014 to 2021). Inflammation of the colon. "Using a 2,4,6-trinitrobenzene sulfonic acid (TNBS)-colitis mouse model it was reported that vanin 1 deficiency protects mice from colitis." (PMID 31404995, 2019). "In humans, elevated VNN1 is associated with pathological conditions, including colitis and systemic sclerosis; in mice, it stimulates the inflammatory response in experimental models of colitis." (PMID 31323030, 2019). "Excess VNN1 promotes inflammation and worsens prognoses in human diseases like colitis and systemic sclerosis." (PMID 31323030, 2019). "Finally, these inhibitors were applied to a mouse colitis model, confirming that vanin-1 is useful in IBD and providing a new therapeutic direction." (PMID 35155380, 2021). "VNN1, increased 49-fold in SSA/Ps by RNA-seq analysis, is an oxidative stress sensor in epithelial cells and plays an important role in mediating inflammatory signals during inflammation-driven carcinogenesis in animal models of colitis-associated colon cancer." (PMID 24533081, 2014). "For example, it is reported that 2,4,6-trinitrobenzenesulfonic acid (TNBS)-induced mouse colitis model, the lack of vanin-1 gene can protect mice from colitis." (PMID 35155380, 2021). "The VNN1 finding, together with increased REG4 and MUC17, that are also increased during colitis, suggests that the development of SSA/Ps may at least in part involve inflammatory processes." (PMID 24533081, 2014).